MBD2 (methyl-CpG binding domain protein 2)
Diseases named in the same sentence as MBD2 in open-access papers (continued):
Sharing a sentence is not in itself a finding about the gene and the disease.
colon carcinoma (5 papers, 2003 to 2022). "HTRA1 is epigenetically silenced in HCT116 colon carcinoma cells via the epigenetic adaptor protein MBD2." (PMID 27388476, 2016). "Similarly, we found the expression of MBD1 and MBD2 was upregulated in MSI colon cancer patients, implying both regulators might involve in immune activation." (PMID 36276973, 2022).
gastric cancer (5 papers, 2013 to 2025). A primary or metastatic malignant neoplasm involving the stomach. "SNORA37, an ELAVL1-facilitated H/ACA box snoRNA derived from host gene MBD2, was up-regulated in gastric cancer tissues and associated with poor outcomes of patients." (PMID 39815331, 2025). "In this study, we identify SNORA37 as an ELAVL1-generated 129-nt H/ACA box snoRNA derived from host gene methyl-CpG binding domain protein 2 (MBD2), which is associated with progression and worse outcomes of gastric cancer." (PMID 39815331, 2025). "Cross-linking RIP assay revealed endogenous binding of ELAVL1 to intron 1 of MBD2 pre-mRNA in gastric cancer cell lines HGC-27 and AGS, which was attenuated by knockdown of ELAVL1." (PMID 39815331, 2025). "In gastric cancer, reduced mRNA expression levels of MBD2 were detected." (PMID 26788506, 2015). "Similarly level of mbd2 mRNA level is significantly lower in gastric cancer tissue than normal gastric mucosa." (PMID 24255851, 2013). "Moreover, silencing of ELAVL1 decreased the levels of SNORA37, without alteration of MBD2 expression, in gastric cancer cells." (PMID 39815331, 2025).
glioma (5 papers, 2016 to 2025). A benign or malignant brain and spinal cord tumor that arises from glial cells (astrocytes, oligodendrocytes, ependymal cells). "miR-520b-mediated MBD2 functions in the progression of glioma." (PMID 33758783, 2021). "Interestingly, the enrichment of MBD3 or the 5mC-binding protein MBD2 indicates entirely opposite outcomes in the glioma survival even though they share a >70% similarity in protein sequences." (PMID 27835581, 2016).
diabetes (4 papers, 2021 to 2025). "On a non-obese diabetic background, mbd2 deficiency upregulates T helper cell 1 programs and exacerbates the development of autoimmune diabetes, and ectopic mbd2 expression in CD4+ T cells reduces the development of diabetes in an adoptive transfer model." (PMID 41198985, 2025). "We monitored the development of spontaneous diabetes in Mbd2−/− NOD mice and littermate counterparts." (PMID 34420035, 2022). "After the adoptive transfer, diabetes was evident by 40 days in NOD.scid mice receiving Mbd2−/− CD4 T cells with all the mice developed hyperglycemia within 57 days, while a relative delay in terms of T1D development was observed in the control group." (PMID 34420035, 2022). "The incidence of diabetes (blood glucose > 13.8 mM) was increased in both female (93.75% vs. 65%, p < 0.001) and male (84.62% vs. 13.33%, p < 0.0001) Mbd2−/− NOD mice along with an early onset of T1D (11.47 ± 1.10 vs. 17.85 ± 1.06 weeks for females, and 14.17 ± 1.06 vs. 29.0 ± 1.0 weeks for males)." (PMID 34420035, 2022).
lung carcinoma (4 papers, 2013 to 2025). "Since lung cancers ((non-small cell lung cancers (NSCLCs) in particular) are one of the highest-ranking causes of cancer-related death worldwide and LUAD is the most prevalent subtype of NSCLCs, we thus first examined MBD2 expression in the lung samples obtained from 69 LUAD patients." (PMID 37142578, 2023).
Obesity (4 papers, 2014 to 2022). Accumulation of substantial excess body fat. "Obesity-associated inflammation changes the splicing preference of methyl-CpG-binding domain protein 2 (MBD2), thus resulting in a greater degree of MBD2_variant2, which in turn promotes the maintenance of cancer stem cells in triple negative BC." (PMID 31661891, 2019).
triple-negative breast carcinoma (4 papers, 2018 to 2025). An invasive breast carcinoma which is negative for expression of estrogen receptor (ER), progesterone receptor (PR), and human epidermal growth factor receptor 2 (HER2). "Moreover, the MBD2 protein level was significantly elevated in the well-known molecular subtypes of human breast tumors [luminal, Her2-positive, and triple-negative breast cancer (TNBC)]." (PMID 38556549, 2024).
bladder cancer (3 papers, 2005 to 2023). "Moreover, a significant reduction in MBD2 mRNA expression was found in human colorectal and gastric cancerous tissues and peripheral blood lymphocytes in bladder cancer patients, implying a protective role for MBD2 in tumorigenesis." (PMID 16168120, 2005).
cervical carcinoma (3 papers, 2022 to 2024). A carcinoma arising from either the exocervical squamous epithelium or the endocervical glandular epithelium. "MBD2 has been linked to various cancers in human, including ovarian carcinoma, renal cell carcinoma, hepatocellular carcinoma, colorectal carcinoma, lung adenocarcinoma, and cervical carcinoma." (PMID 39676597, 2024). "Specifically, MBD2 has been shown to promote the progression and poor prognosis of renal cell carcinoma, while MBD4 has been associated with cervical cancer polymorphism." (PMID 37370795, 2023). "A study shows that MBD2 expression is significantly reduced in cervical cancer." (PMID 39676597, 2024).
dermatomyositis (3 papers, 2016 to 2021). Dermatomyositis (DM) is a type of idiopathic inflammatory myopathy characterized by evocative skin lesions and symmetrical proximal muscle weakness. "The NuRD multiprotein complex includes the dermatomyositis-specific Mi2 autoantigen (Mi2-β), RB-associated proteins 46 and 48 (RbAp46 and RbAp48), MBD2 and MBD3, and metastasis-associated proteins 2 and 3 (MTA2 and MTA3)." (PMID 26810492, 2016).
hepatocellular carcinoma (3 papers, 2008 to 2026). A malignant tumor that arises from hepatocytes. "The CpG island of this gene becomes hypermethylated during the pathogenesis of human hepatocellular carcinoma and MBD2 appears bound to GSTP1 promoter region leading to gene silencing." (PMID 18542062, 2008). "MBD2 has also been related to GSTP1 DNA methylation-dependent silencing in hepatocellular carcinoma." (PMID 18542062, 2008).
intestinal cancer (3 papers, 2018 to 2020). "Although Mbd2 is widely expressed in gastrointestinal immune cells and is implicated in regulating intestinal cancer, anti-helminth responses and colonic inflammation, the Mbd2-expressing cell types that control these responses are incompletely defined." (PMID 32117307, 2020).
lung adenocarcinoma (3 papers, 2023 to 2025). A carcinoma that arises from the lung and is characterized by the presence of malignant glandular epithelial cells. "Reduced MBD2 levels were associated with increased metastasis and poorer survival in lung adenocarcinoma patients." (PMID 40520993, 2025). "Mechanistic studies investigating the epithelial-to-mesenchymal transition (EMT) suppressive function of MBD2, another crucial protein involved in the methylation process, demonstrated a positive correlation between MBD2 and the miR-200 family in lung adenocarcinoma." (PMID 37239435, 2023). "However, in lung adenocarcinoma, MBD2 inhibits the malignant characteristic." (PMID 39676597, 2024). "In lung adenocarcinoma, Pei et al58 discovered that TET1 formed a complex with methyl-CpG binding domain protein 2 (MBD2) to activate miR-200s, key regulators of tumor invasiveness." (PMID 40520993, 2025).
psoriasis (3 papers, 2016 to 2025). An autoimmune condition characterized by red, well-delineated plaques with silvery scales that are usually on the extensor surfaces and scalp. "However, MBD2 was notably downregulated in PBMCs from the disease group, and the mechanisms through which MBD2 might contribute to psoriasis development remain largely unexplored." (PMID 40533455, 2025).
renal fibrosis (3 papers, 2022 to 2025). A final common manifestation of a wide variety of chronic kidney diseases characterized by glomerulosclerosis and tubulointerstitial fibrosis. "We also discovered the molecular mechanism underlying MBD2-induced renal fibrosis in UUO and ischemic injury via upregulation of the expression of G0S2." (PMID 35136032, 2022). "Research has shown that attenuation of TGF-β1, UUO and I/R treatment-induced renal fibrosis through MBD2 silencing or PT-MBD2-KO is due to MBD2 directly leading to increased expression of EGR1 and inducing hypomethylation in the promoter region." (PMID 37742034, 2023). "Together, these results provided substantial evidence to support the theory that MBD2 in macrophages is a therapeutic target for renal fibrosis." (PMID 35136032, 2022). "The absence of MBD2 in macrophages significantly reduced the M2-biased macrophage phenotype, suggesting that MBD2 may also regulate macrophage M2 programs in an asthmatic setting, consistent with previous findings in renal fibrosis." (PMID 40533455, 2025). "Hence, we have to reevaluate the role and mechanism of MBD2 in the differentiation of resting M0 macrophages and renal fibrosis." (PMID 35136032, 2022). "Although MBD2 has been considered the most promising target for DNA demethylation therapy in tumor disease, its role in macrophages differentiation and renal fibrosis remained largely unknown." (PMID 35136032, 2022). "In summary, to our knowledge, this is the first report that MBD2 in macrophages could act as an inducer of renal fibrosis." (PMID 35136032, 2022). "We hypothesized that MBD2 in macrophages might promote the differentiation of resting M0 macrophages to mediate the renal fibrosis by upregulating the expression of G0S2." (PMID 35136032, 2022). "However, the role and mechanism of action of MBD2 in macrophages differentiation and renal fibrosis remain largely unknown." (PMID 35136032, 2022). "Thus, this study suggested that MBD2 in macrophages might be an attractive therapeutic target for renal fibrosis." (PMID 35136032, 2022). "The attenuation of renal fibrosis in mice subjected to UUO and I/R was first demonstrated upon knockdown or silencing of MBD2 in macrophages, an effect attributed to its binding to GS02." (PMID 40533455, 2025). "In this study, we verified that inhibition of MBD2 in macrophages attenuated TGF-β1- and UUO and I/R-induced renal fibrosis." (PMID 35136032, 2022). "In vivo, MBD2 LysMcre attenuated unilateral ureteral obstruction (UUO) and ischemia/reperfusion (I/R)-induced renal fibrosis via downregulation of G0S2, which was demonstrated by the downregulation of fibronectin (FN), collagen I and IV, α-SMA, G0S2." (PMID 35136032, 2022).
acute kidney injury (2 papers, 2017 to 2021). Sudden and sustained deterioration of the kidney function characterized by decreased glomerular filtration rate, increased serum creatinine or oliguria. "Our study investigated the role of Methyl‐CpG–binding domain protein 2 (MBD2) in RM‐induced acute kidney injury (AKI) both in vitro and in vivo." (PMID 33764669, 2021). "At day 7, VAN treatment induced moderate renal failure in wild-type mice, which was significantly suppressed in MBD2 KO mice." (PMID 29022913, 2017).
age-related macular degeneration (2 papers, 2022 to 2023). Age-related loss of vision in the central portion of the retina (macula), secondary to retinal degeneration. "MBD2 protein is reported to mediate apoptosis in retinal ganglion cells, and possibly play a role in the pathogenesis of age-related macular degeneration." (PMID 37359372, 2023).
autism (2 papers, 2013 to 2023). Persistent deficits in social interaction and communication and interaction as well as a markedly restricted repertoire of activity and interest as well as repetitive patterns of behavior. "TRIM27 is a DNA-binding protein associated with the nuclear matrix and interacts with methyl-CpG-binding domain (MBD) proteins, including MBD2, MBD3 and MBD4, and rare autism-specific protein-changing alterations have been observed both in MBD3 and MBD4." (PMID 24047820, 2013).
breast tumors (2 papers, 2024). "There are several other advantages of using transgenic KO models to study the role of Mbd2 in breast tumor progression." (PMID 38556549, 2024). "Importantly, loss of the Mbd2 gene impairs the activation of the PI3K/AKT pathway, which is required for PyMT-mediated oncogenic transformation, growth, and survival of breast tumor cells." (PMID 38556549, 2024). "Since several prometastatic genes (Plau, Mmp2, Mmp9, Has2, and Has3) were downregulated in Mbd2-KO PyMT tumors, we next used formalin-fixed lung tissue sections collected at the experimental endpoint and stained them with hematoxylin and eosin (H&E) to assess breast tumor metastasis to the lung." (PMID 38556549, 2024). "Therefore, we next analyzed the RNA-Seq data obtained from breast tumors to determine whether the expression of immune-related genes is altered upon Mbd2 deletion in PyMT mice." (PMID 38556549, 2024).
esophageal cancer (2 papers, 2015 to 2024). A primary or metastatic malignant neoplasm involving the esophagus. "MBD2 is a member of the MBD protein family, the expression of which is reduced in esophageal cancer." (PMID 25823933, 2015).
experimental autoimmune encephalomyelitis (2 papers, 2021 to 2022). An autoimmune demyelinating disease of the central nervous system that is produced experimentally in animals by the injection of homogenized brain or spinal cord in Freund's adjuvant. "Similarly, unsuppressed Tbet/Hlx axis results in deficiency of Th17 cell differentiation in MBD2-/- mice with the protection from experimental autoimmune encephalomyelitis, showing the role of MBD2 in Th17 differentiation." (PMID 35096261, 2021). "The deletion of Mbd2 rendered it incapable of “reading” methylation information, which disrupted the homeostasis of the T-bet/H 2.0-like homeobox axis and inhibited the differentiation of T-helper type 17 cells, thereby protecting against experimental autoimmune encephalomyelitis." (PMID 36582430, 2022).
intracranial aneurysm (2 papers, 2023 to 2025). "Conversely, MBD2 was found to be associated with an increased risk of unruptured intracranial aneurysm, underscoring the complex nature of the epigenetic mechanisms underlying IA." (PMID 37742034, 2023).
keratitis (2 papers, 2015 to 2024). A corneal disease that is characterized by inflammation of the cornea. "Moreover, GLY treatment enhances the levels of antimicrobial proteins like CRAMP and Methyl-CpG binding domain protein 2 (MBD2), contributing to a protective effect against P. aeruginosa-induced keratitis." (PMID 38930536, 2024). "Our findings that transcripts for the antimicrobial peptides mBD2, mBD3 and CRAMP were increased in Pglyrp-2-/- may in part explain the observed improvement in bacterial clearance and efficacious resolution of keratitis in these mice." (PMID 26332373, 2015).
leukemia (2 papers, 2021 to 2023). A malignant (clonal) hematologic disorder, involving hematopoietic stem cells and characterized by the presence of primitive or atypical myeloid or lymphoid cells in the bone marrow and the blood. "The latent period of recipient mice with MLL-AF9-transformed Mbd2−/− cells was significantly longer than that of the WT mice, indicating that MBD2 deficiency delayed leukemia onset." (PMID 34789717, 2021). "Our microarray analysis indicated that MBD2 ablation partially reverses the expression of MLL leukemia-associated gene signature." (PMID 34789717, 2021). "Herein, by using an MLL-AF9 murine model and a human AML cell line, we observed that loss of MBD2 could delay the initiation and progression of leukemia." (PMID 34789717, 2021). "In Notch1-driven T-cell acute lymphoblastic leukemia (T-ALL), we first noted that MBD2 is required for the progression and maintenance of leukemia." (PMID 37142578, 2023). "Intriguingly, we found that MBD2 depletion reduced colony formation in leukemia cells, increased differentiation, and delayed leukemogenesis by arresting the cell cycle of LSCs." (PMID 34789717, 2021). "Compared with the WT conditions, the loss of MBD2 significantly decreased the number of white blood cells (WBCs) and leukemic cell infiltration in the peripheral blood, which was consistent with the reduced leukemia burden in Mbd2−/− AML mice." (PMID 34789717, 2021). "To investigate the functional impact of MBD2 deletion on the development of MLL-AF9-driven leukemia, we generated a serial transplantation mouse model." (PMID 34789717, 2021). "To determine how MBD2 regulates the proliferation of LSCs, we assessed the cell cycle status of leukemia cells." (PMID 34789717, 2021). "Therefore, our data demonstrate that MBD2 depletion enhances myeloid differentiation of leukemia cells and probably leads to delayed AML progression." (PMID 34789717, 2021). "MBD2 depletion significantly reduced the leukemia burden by decreasing the proportion of leukemic stem cells (LSCs) and inhibiting leukemia cell proliferation in serial transplantation experiments, thereby allowing leukemic blasts to transition to a more mature state reflecting normal myelopoiesis." (PMID 34789717, 2021). "Flow cytometric analysis also demonstrated that MBD2 depletion increased the expression of myeloid differentiation markers Mac-1 and Gr-1 in the Mbd2−/− group since Mac-1+/Gr-1+ cells represent a more mature leukemia cell population." (PMID 34789717, 2021). "Our BSP analysis demonstrated that the methylation levels of CDKN1C promoter are significantly higher in AML patients than that of the healthy controls, and MBD2 deficiency did not affect the methylation status of CDKN1C promoter regions in leukemia cells." (PMID 34789717, 2021). "We next assessed the functional role of MBD2 in human MLL-rearranged leukemia." (PMID 34789717, 2021). "Consistent with the DAVID analysis results, the GSEA plot showed downregulation of the cell cycle signature, decreased expression of an LSC signature, and increased expression of the myeloid differentiation signature in Mbd2−/− leukemia cells compared with control cells." (PMID 34789717, 2021). "In this study, we demonstrated that MBD2 deletion delayed MLL-AF9 leukemia onset." (PMID 34789717, 2021). "Furthermore, in comparison with their WT counterparts, GFP+ leukemia cells of Mbd2−/− mice presented more leukemic blast cells with segmented nuclei in the morphological analysis, which suggested increased myeloid differentiation after MBD2 deletion." (PMID 34789717, 2021). "Mbd2−/− colonies were smaller and more diffuse than WT colonies, supporting the role of MBD2 in promoting leukemia transformation." (PMID 34789717, 2021). "WT leukemia samples from our study clustered with leukemia samples from the GSE34185 dataset, whereas Mbd2−/− samples from our study clustered with normal BM samples from the GSE34185 dataset." (PMID 34789717, 2021).